UBE2D3 (ubiquitin conjugating enzyme E2 D3)
Diseases named in the same sentence as UBE2D3 in open-access papers (continued):
Sharing a sentence is not in itself a finding about the gene and the disease.
periodontitis (1 paper, 2025). An acute or chronic inflammatory process that affects the tissues that surround and support the teeth. "And more well‐designed clinical studies are needed to provide evidence on the association between UBE2D3 and periodontitis." (PMID 39811801, 2025). "Fifth, the association between UBE2D3 and periodontitis requires collection of human samples from clinical healthy groups and periodontitis groups." (PMID 39811801, 2025). "In this study, we examined the therapeutic role of EB on periodontitis, synthesized the specific probe of EB and screened the direct target protein UBE2D3 by activity‐based protein profiling (ABPP) method using this probe for the first time." (PMID 39811801, 2025). "Our findings suggest that EB improves inflammation and bone destruction in periodontitis by directly targeting UBE2D3." (PMID 39811801, 2025). "To further investigate the specific role of UBE2D3 underlying the anti‐inflammatory activity and effect of EB on periodontitis, we transfected siRNA in Raw264.7 cells to knockdown (KD) Ube2d3." (PMID 39811801, 2025). "Taken together, EB ameliorates periodontitis by targeting UBE2D3 to suppress the ubiquitination degradation of IκBα, leading to inactivation of nuclear transcription factor‐κB signaling pathway." (PMID 39811801, 2025). "By using an array of chemical biology approaches, direct binding protein target, UBE2D3, and mechanisms of actions of Eupalinolide B in the treatment of periodontitis were revealed." (PMID 39811801, 2025). "Inhibition of UBE2D3‒NF‐κB signaling by EB may contribute to alleviating the progression of periodontitis." (PMID 39811801, 2025). "Our results suggested that EB may be a new kind of UBE2D3 inhibitor and may become a promising therapeutic agent for anti‐periodontitis." (PMID 39811801, 2025).
virus infection (1 paper, 2017). "Here we identify two ubiquitin enzymes Ube2D3 and Ube2N through chromatographic purification as activators for RIG-I on virus infection." (PMID 28469175, 2017). "Disruption of both Ube2D3 and Ube2N expression abrogated the IFN induction following virus infection." (PMID 28469175, 2017). "Remarkably, when Ube2Ds or Ube2N was ectopically expressed in si-Ube2D3/Ube2N−/− cells, MAVS aggregation could be fully restored on virus infection, and IFN induction was also rescued." (PMID 28469175, 2017). "As expected, Ube2D3 was not able to rescue the defect of IFN induction by viral infection in sh-Ube2N-treated cells." (PMID 28469175, 2017). "Consistently, MAVS could not form aggregates on virus infection in the absence of both Ube2D3 and Ube2N." (PMID 28469175, 2017).
tumor (15 papers, 2008 to 2025). "High expression of UBE2D1 and UBE2D3 can promote the proliferation, invasion and metastasis of tumor cells, and inhibit the apoptosis of tumor cells." (PMID 37886979, 2023). "This supports the role of this lncRNA in promoting tumor growth and development through the UBE2D3/IκBa-mediated NF-κB regulatory axis." (PMID 38041015, 2023). "While UBE2D3 has been described to be an in vitro tumor suppressor for its role in modulating radiosensitivity and proliferation, the in vivo data of TCGA suggested that higher UBE2D3 expression predicts poorer clinical outcomes." (PMID 27959953, 2016). "It was also identified that traditional factors, including tumor location, T stage, lymph node status, TNM stage, and molecular factors of hTERT and UBE2D3, were significantly associated with overall survival time (P<0.05 for all)." (PMID 25789002, 2015). "In this study, we demonstrated that UBE2D3 overexpression could increase radiosensitivity of EC109 cells by degradating hTERT, a key factor associated with radiosensitivity of tumor cells." (PMID 27105523, 2016). "Lastly, five genes including GSKIP, SELENOF, RAP1B, UBE2D3, and GTF2B, were found to be co-expressed in both adjacent healthy tissue and tumor tissue." (PMID 37365287, 2023). "The SHP-2 inhibitor PHPS1 reversed the tumor-suppressive effects of UBE2D3 knockdown, while SHP-2 overexpression blocked the oncogenic effects of UBE2D3 overexpression." (PMID 34195079, 2021). "However, the mechanism by which the ubiquitination process of UBE2D3 is involved in the interaction with the hTERT pathway, and whether UBE2D3 expression exists as a universal phenomenon in all types of tumor, requires additional studies to be conducted in the future." (PMID 25789002, 2015). "Notably, transcriptomic data and RTqPCR results demonstrated that while PUM2 and HIF3A were highly expressed in normal tissues, DDB1 showed increased expression in tumor tissues, with CUL1, COPS2, and UBE2D3 remaining unchanged." (PMID 40524221, 2025). "The results indicated that while UBE2D3 expression did not significantly differ between tumor and normal tissues, it influenced the expression of IL6 and IL8, downstream factors of the NF-κB signaling pathway by regulating IκBa expression." (PMID 38041015, 2023). "These two studies indicated that UBE2D3 expression is involved in cell cycle regulation via the degradation of cyclin D1; in consideration of this biological behavior, the present study proposes that UBE2D2 expression levels may promote tumor development." (PMID 25789002, 2015). "However, in the absence of UBE2D3, cyclin D1 is not degraded and tumor cells continue to cycle." (PMID 25789002, 2015). "Transcriptomic data and RT-qPCR findings indicated that PUM2 and HIF3A exhibited high expression levels in normal tissues, while DDB1 showed increased expression in tumor tissues; no significant changes were observed for CUL1, COPS2, and UBE2D3." (PMID 40524221, 2025). "The expression of UBE2D3,p-STAT3, HK-2 and PFKL was reduced in the tumor of the shUBE23D group whereas that of STAT3 exhibited no significant alternation." (PMID 34195079, 2021).
cancer (12 papers, 2008 to 2025). A tumor composed of atypical neoplastic, often pleomorphic cells that invade other tissues. "Of these targets, CDCP1 is reportedly associated with PI3K/AKT signaling, CMTM6 is a critical regulator of PD-L1 in a broad range of cancer cells, while UBE2D3 is linked to NF-κB signaling and ADAM10 plays a role in TNF signaling." (PMID 38041015, 2023). "Although hTERT expression has been shown to be negatively associated with radiosensitivity of various of cancers including EsC, little is known about the role of UBE2D3 in radiosensitivity of EsC." (PMID 27105523, 2016). "UBE2D3 is mutated, and its expression level is altered in a wide variety of cancers, including breast, ovarian, cervical, head and neck and esophageal cancer, melanoma, leukemia, and multiple myeloma (Oncomine, EMBL-EBI Expression Atlas, Cosmic, and ICGC databases)." (PMID 37059365, 2023). "Our previous study initially determined that downregulation of UBE2D3 expression increases hTERT expression and cell proliferation, however, the association between the expression of these two proteins and their functions in cancer tissues remains unknown." (PMID 25789002, 2015). "It has been reported in recent studies that UBE2D3 participated in the regulation of different inflammatory diseases and cancer, making it an attractive molecular drug target." (PMID 39811801, 2025). "Ube2d3 is abnormally highly expressed in a variety of human cancers and immune diseases and participated in the progression of these diseases such as esophageal, breast, pancreatic, and colorectal cancer." (PMID 39811801, 2025). "Ubiquitin-conjugating enzyme E2 D3 (UBE2D3) is involved in the pathogenesis of various kinds of cancer." (PMID 34195079, 2021). "Furthermore, UBE2D3 levels affect responses to cancer cell treatment with radiation or all-trans retinoic acid (ATRA)." (PMID 37059365, 2023). "It would be interesting to address whether this is regulated by UBE2D3 and whether UBE2D3 levels are potentially also increased in these cancers." (PMID 37059365, 2023). "Therefore, LOXL2, UBE2D1, UBE2D3, and DβH can be considered as potential candidates for cancer diagnosis, prognosis, and therapeutic biomarkers." (PMID 37886979, 2023).
neurodegenerative disease (2 papers, 2023 to 2025). A disorder of the central nervous system characterized by gradual and progressive loss of neural tissue and neurologic function. "By regulating SQSTM1 and HSPA5 ubiquitination and regulating SQSTM1 activity, UBE2D3 could potentially contribute to clearance of aggregates and thereby help in reducing the chance of development of neurodegenerative diseases." (PMID 37059365, 2023).
UBE2D3 also shares sentences with these, for which no sentence is quoted: pancreatic cancer (3 papers); colorectal cancer (1); gastric cancer (1); Glioblastoma multiforme (1); lung carcinoma (1); myocardial ischemia (1); prostate carcinoma (1); psoriasis (1); psychiatric disorder (1); sarcoma (1); type 2 diabetes (1).